DDX3X (DEAD-box helicase 3 X-linked)
Diseases named in the same sentence as DDX3X in open-access papers (continued):
Sharing a sentence is not in itself a finding about the gene and the disease.
Ogden syndrome (1 paper, 2017). Ogden syndrome is a rare, genetic progeroid syndrome characterized by a variable phenotype including postnatal growth delay, severe global developmental delay, hypotonia, non-specific dysmorphic facies with aged appearance and cryptorchidism, as well as cardiac arrthymias and skeletal anomalies. "Hemizygous variants were identified in two known X-linked disease genes: NAA10 (Ogden syndrome, ID and long QT, MIM 300855); and DDX3X previously associated with X-linked ID (MIM 300958)." (PMID 28327206, 2017).
osteoarthritis (1 paper, 2023). A noninflammatory degenerative joint disease occurring chiefly in older persons, characterized by degeneration of the articular cartilage, hypertrophy of bone at the margins and changes in the synovial membrane. "In order to further understand the possible mechanism of miR-181a-5p regulating the inflammatory response of osteoarthritis cells, we found that DDX3X is the target of miR-181a-5p through bioinformatics analysis." (PMID 37587519, 2023). "The results suggested that the occurrence of osteoarthritis is related to the abnormal expression of miR-181a-5p and DDX3X." (PMID 37587519, 2023). "In this paper, first, we screened the osteoarthritis dataset (GSE206848) by GEO for differential gene analysis, and then used Cytoscape and Mcode plugin to screen out the key gene DDX3X." (PMID 37587519, 2023).
periodontitis (1 paper, 2022). An acute or chronic inflammatory process that affects the tissues that surround and support the teeth. "The results clarified lncZFY-AS1 and DEAD-Box Helicase 3 X-Linked (DDX3X) were up-regulated, but microRNA (miR)-129-5p was down-regulated in periodontitis." (PMID 35659193, 2022). "In terms of mechanism, repressive lncZFY-AS1 reduced NF-κB inflammation signaling pathway protein, and accelerated antioxidant signaling pathway Nrf2/HO-1 protein to relieve periodontitis via competitively combining with miR-129-5p and depressing DDX3X." (PMID 35659193, 2022). "All in all, the results of this study clarify that lncZFY-AS modulates the Nrf2/HO-1 and NF-κB signaling pathways in periodontitis via competitively adsorbing miR-129-5p to mediate DDX3X, which helps to facilitate the deterioration of periodontitis." (PMID 35659193, 2022). "LncZFY-AS/miR-129-5p/DDX3X axis is supposed to be applied as an information target for the treatment of periodontitis later." (PMID 35659193, 2022). "In conclusion, these data suggest lncZFY-AS1 promotes inflammatory injury and oxidative stress in periodontitis by competitively binding to miR-129-5p and mediating DDX3X expression." (PMID 35659193, 2022). "Repressive lncZFY-AS1’s depression on inflammation, oxidative damage and apoptosis of hPDLCs was reversed via elevated DDX3X, which suggested that DDX3X was a key protein modulated by lncZFY-AS1 in periodontitis." (PMID 35659193, 2022). "In this study, it was discovered that DDX3X was up-regulated in periodontitis." (PMID 35659193, 2022). "LncZFY-AS1/miR-129-5p/DDX3X may serve as a novel molecular target for treatment of periodontitis in the future." (PMID 35659193, 2022). "In addition, whether lncZFY-AS1/miR-129-5p/DDX3X can be applied as a therapeutic target for patients with periodontitis requires to be verified in clinical studies." (PMID 35659193, 2022).
primary immunodeficiency (1 paper, 2025). "It is not classified as a primary immunodeficiency per se, but may arise in the context of acquired somatic mutations (e.g., STAT3, DDX3X, or BCOR) or immune dysregulation affecting EBV control." (PMID 40863427, 2025).
psoriasis (1 paper, 2022). An autoimmune condition characterized by red, well-delineated plaques with silvery scales that are usually on the extensor surfaces and scalp. "It is probably that AP-1 binding induces DDX3X expression, further activates NLRP3 inflammasomes to mediate psoriasis, and leads to lymphocyte infiltration in psoriatic lesions." (PMID 35277199, 2022).
pulmonary arterial hypertension (1 paper, 2025). Pulmonary arterial hypertension (PAH) is a group of diseases characterized by mean pulmonary artery pressure >20 mmHg and elevated pulmonary arterial resistance leading to right heart failure. "Here, we describe a female infant with a mutation in the DDX3X gene, pulmonary arterial hypertension, and Snijders Blok–Campeau syndrome." (PMID 40710838, 2025). "Although the basic biochemical function of DDX3X is well understood, further research on a larger cohort of DDX3X patients is needed to evaluate associations with vasculopathies such as pulmonary arterial hypertension." (PMID 40710838, 2025).
renal clear cell carcinoma (1 paper, 2020). "The DDX3X-dependent prognosis in renal chromophobe is distinct from renal clear cell carcinoma, suggesting the diversity regarding DDX3X’s potential impacts on tumor progression." (PMID 32326089, 2020).
Stroke (1 paper, 2023). Sudden impairment of blood flow to a part of the brain due to occlusion or rupture of an artery to the brain. "RIC significantly increased G3BP1, TIA1, and DDX3X levels in mRNA and protein expressions at Day 3 after stroke." (PMID 37580991, 2023).
T-cell acute lymphoblastic leukaemia (1 paper, 2021). "DDX3X is one of the partners of MLLT10 in adult and paediatric T-cell acute lymphoblastic leukaemia (T-ALL)." (PMID 33627125, 2021). "In T-cell acute lymphoblastic leukaemia (T-ALL), the fusion of DDX3X with MLLT10 preserves the N-terminus of DDX3X, which contains the NES and eIF4E binding site." (PMID 33627125, 2021).
tauopathies (1 paper, 2023). "FUS and TARDBP are FTLD genes, and DDX3X and TIA1 have been implicated in tauopathies." (PMID 37730840, 2023).
viral pneumonia (1 paper, 2022). Inflammation of the lung parenchyma that is caused by a viral infection. "Nevertheless, our data suggest that TRPV4 inhibitors may represent an attractive therapy for viral pneumonia as they may both suppress viral load via DDX3X signaling and dampen the associated inflammatory response via the S100A7/RAGE pathway." (PMID 35396513, 2022).
cancer (176 papers, 2011 to 2026). A tumor composed of atypical neoplastic, often pleomorphic cells that invade other tissues. "Beyond neurodevelopment, missense mutations in DDX3X also cause diverse cancers including medulloblastoma." (PMID 39836689, 2025). "DDX3X is ubiquitously transcribed and translated, and has been associated with various diseases such as birth defects, viral infection, inflammation, and cancer." (PMID 39975375, 2025). "DEAD-box helicase 3 X-linked (DDX3X) is a frequently mutated gene in various cancers, including LAML." (PMID 40564907, 2025). "NCV formulation modulated the expression of genes associated with cancer proliferation, such as DDX3X and Ki-67, in various cancer cell lines, suggesting a synergistic effect of the vitamins and cisplatin in combating cancer." (PMID 40507930, 2025). "By employing a combination of pan-cancer transcriptomics, mutational profiling, survival analyses, and molecular docking, we identified DDX3X as a highly mutated and differentially expressed gene in LAML." (PMID 40564907, 2025). "DDX3X is a promising target for therapeutic interventions considering its essential role in RNA metabolism and its mutation-driven dysregulation in cancer; however, it has been underutilized as a therapeutic target." (PMID 40564907, 2025). "DDX3X encodes a multi-functional RNA helicase, with mutations causing developmental disorders and cancers." (PMID 39026797, 2024). "Mutations in DDX3X are associated with a variety of human diseases including cancers and developmental delay." (PMID 38273160, 2024). "Given its central role in inflammasome-mediated cell death, and considering the frequent mutations of DDX3X found in various cancers, it presents as a potential target for anticancer therapies." (PMID 38265972, 2024). "Variant types are disease selective in DDX3X, with cancers ranging from primarily loss-of-function alleles in NK-TCL and other blood cancers to nearly exclusively missense variants in medulloblastoma." (PMID 38273160, 2024). "DDX3X has considerable functional value in various cancer types, so identification of genetic targets linked to this gene is the topic of many research efforts." (PMID 38316768, 2024). "Overexpression of DDX3X, here identified as a drug target, has been reported in many cancers and is associated with poor survival rates of cancer patients." (PMID 37975412, 2024). "This suggests that DDX3X predominantly operates as a tumour suppressor gene, and that this variant effect map identifies almost all of the cancer driver mutations." (PMID 38057330, 2023). "Emerging evidence indicates the critical regulatory role of DEAD (Asp-Glu-Ala-Asp) Box Polypeptide 3, X-Linked (DDX3X) in cancer progression." (PMID 37371098, 2023). "DDX3X is also a somatically mutated cancer driver gene proposed to have tumour promoting and suppressing effects." (PMID 38057330, 2023). "Here, the authors perform saturation genome editing of DDX3X to test the functional impact of 12,776 variants, develop a machine learning classifier to identify variants relevant for NDD, and show that DDX3X predominantly acts as a tumour suppressor in cancer." (PMID 38057330, 2023). "Mechanistically, cancer-associated DDX3X mutants have reduced RNA-dependent ATPase activity, and their expression leads to increased stress granule assembly." (PMID 35626643, 2022). "In these cancer types, a high DDX3X expression level is always linked to a poor clinical outcome, confirming the potential oncogenic role in controlling tumor proliferation and progression." (PMID 35954483, 2022). "In this type of cancer, the levels of DDX3X protein expression are differentially linked to survival or cancer progression, depending on the tumor type." (PMID 35954483, 2022).
cancer (continued). "For example, somatic mutations in DDX3X were identified in various human cancers, and de novo germline mutations cause a neurodevelopmental condition now termed ‘DDX3X syndrome’." (PMID 36393867, 2022). "Regulation of Cyclin E translation linked DDX3X to cell growth control and G1/S regulation, which carries strong implications for its role in cancer." (PMID 36393867, 2022). "Based on literature data, several DDX3X unique interactors were found associated with different cancer types." (PMID 35954483, 2022). "DDX3X mutations have also been linked to cancer progression, including medulloblastoma, many of which overlap with ID-associated mutations." (PMID 35762573, 2022). "Instead of a general translation defect, our data suggest that the major functional consequence of mutations in DDX3X is to promote cancer through more specific effects on translation." (PMID 33460649, 2021). "BPDE (benzopyrene diol epoxide), a major cancer-causing compound, induces consistent activation of DDX3X in the immortalized human breast cell line MCF10A." (PMID 33627125, 2021). "Through Pearson’s correlation coefficient analysis (|R2|> 0.3 and P< 0.05), 206 transcription factors were associated with cancer driver gene expression, and DDX3X, JAK1, EGR2, IKZF3, and CCR7 were the five most enriched cancer driver genes." (PMID 34507558, 2021). "The combination of ionizing radiation and DDX3X inhibition causes cancer cells to undergo metabolic catastrophe, which is a promising anti-tumour therapeutic strategy." (PMID 33627125, 2021). "In sum, the cancer protective potential of KDM6A and DDX3X in normal females preferentially, is emphasised by our data, which also reinforces their particular mutation risk in male cancers." (PMID 31772231, 2019). "We found evidence for DDX3X having multiple impacts on cancer progression, and evaluated DDX3X expression levels in a pancancer panel and its associations with patient survival in each cancer-type cohort." (PMID 31906196, 2019). "The human ATPase/RNA helicase X-linked DEAD-box polypeptide 3 (DDX3X) emerged as a novel therapeutic target in the fight against both infectious diseases and cancer." (PMID 31690062, 2019). "Elucidating the precise mechanism whereby induction of SG assembly and inhibition of translation by mutations in DDX3X contribute to cancer remains to be determined but is only growing in importance." (PMID 27180681, 2016). "We found that cancer-related DDX3X mutations were associated with hyper-assembly of SGs that was accompanied by a striking impairment in mRNA translation." (PMID 27180681, 2016). "The high recurrence of somatic DDX3X mutations in numerous cancer types suggests that perturbation of translational regulation by DDX3X plays an important role in tumor development." (PMID 27180681, 2016). "To further evaluate the role of SG hyper-assembly in the translation defect caused by cancer-associated DDX3X mutations we took advantage of two RNA-binding proteins that are essential to SG assembly, G3BP1 and G3BP257." (PMID 27180681, 2016). "DDX3X expression was associated with upregulation of Sox2 and increase of cancer cells exhibiting CSC-like phenotypes, such as anchorage-independent proliferation, strong expression of CD44, and aldehyde dehydrogenase (ALDH)." (PMID 25343452, 2014). "Notably, DDX3X undergoes liquid–liquid phase separation (LLPS) and overexpression of DDX3X missense variants causes stress granule formation in cancer cells and neural cells." (PMID 39836689, 2025).
cancer (continued). "Human DDX3X mutations are associated with several neurodevelopmental disorders and cancers." (PMID 39026797, 2024). "Further cancer-associated mutations in DDX3X can drive SG assembly." (PMID 38539466, 2024). "A separate study in lung cancer cells harboring epidermal growth factor receptor (EGFR)-activating mutations found that preferential expression of DDX3X induced a cancer stem cell-like phenotype, increasing EMT as well as a loss of sensitivity to EGFR-tyrosine kinase inhibitors." (PMID 38539466, 2024). "Given that specific mutations in a protein may affect its biological function, we searched the Cancer Cell Line Encyclopedia and collected 6 natural missense mutations of DDX3X in cancer." (PMID 37988165, 2023). "Moreover, functionally-abnormal variants can account for almost all of the excess nonsynonymous DDX3X somatic mutations seen in DDX3X-driven cancers." (PMID 38057330, 2023). "For example, somatic mutations in DDX3X are identified in various cancers." (PMID 36761420, 2022). "Several other DDX3X targets have been linked to cancer, implicating DDX3X in tumorigenesis." (PMID 36393867, 2022). "Altogether, these clinical findings argue that DDX3X mutations are deleterious and suggest that cell cycle defects may underlie their association with cancer and ID." (PMID 35762573, 2022). "Multiple specific mutations in DDX3X are associated with cancer." (PMID 35626643, 2022). "Since translation is the most energy-intensive process in a cell, a reduced rate of translation caused by DDX3X mutations might allow for the metabolic adaptation of cancer cells for their continued proliferation." (PMID 35626643, 2022). "In addition to BLM and WRN, mutations in DDX3X have been associated with several diseases, specifically several cancers, epilepsy, and female intellectual disability." (PMID 35626643, 2022). "The study of DDX3X in cancer involves in proliferation, metastasis, genome mutation and so on." (PMID 33627125, 2021). "This unique property of DDX3X might explain why cancers caused by a reduction or loss in DDX3X expression mostly occur in male patients." (PMID 33627125, 2021). "Actually, prevalence of DDX3X somatic mutations has been found in cancer patients." (PMID 31906196, 2019). "Whether cancer-related mutations in DDX3X influence SG formation, and additionally, differentially target mRNAs under stress remains unknown." (PMID 27058758, 2016). "We undertook a comprehensive, unbiased evaluation of DDX3X function and the consequences of DDX3X missense mutations in cancer by analyzing a spectrum of these mutations occurring in MB tumors using cell biological, biochemical, genomic, and proteomic approaches." (PMID 27180681, 2016). "This work provides mechanistic insights into the consequences of cancer-related DDX3X mutations, suggesting that globally reduced translation may provide a context-dependent survival advantage that must be considered as a possible contributor to tumorigenesis." (PMID 27180681, 2016). "Notably, downregulation of DDX3X in human cancer lines also causes R-loops." (PMID 39836689, 2025). "SGE-depleted variants (but not SGE-enriched variants) were significantly over-represented in cancer types in which DDX3X has been shown to be a driver gene, and could account for almost all of the excess non-synonymous DDX3X somatic mutations seen in these cancers." (PMID 38057330, 2023). "Therefore, careful interpretation may be required to understand DDX3X mutations between blood and solid types of cancers." (PMID 35874614, 2022). "Thus, it is likely that sensitivity to DDX3X inhibition does not only depend on its expression levels but also on the genetic background associated with a specific cancer phenotype, which is in agreement with the multifaceted roles of DDX3X in tumor transformation." (PMID 34771731, 2021).